KMT2A (lysine methyltransferase 2A)
Diseases named in the same sentence as KMT2A in open-access papers (continued):
Sharing a sentence is not in itself a finding about the gene and the disease.
acute leukemia (continued). "Therapeutic disruption of the interactions between menin and the KMT2A-fusion protein complex has demonstrated single-agent clinical responses for patients with KMT2A-rearranged acute leukemia." (PMID 38892207, 2024). "Recently, menin inhibitors like revumenib have garnered attention for their potential therapeutic efficacy in treating KMT2A-rearranged acute leukemias." (PMID 38892207, 2024). "A comprehensive review was carried out by systematically synthesizing existing literature on PubMed, using the combination of the keywords ‘KMT2A‐rearranged acute leukemia’, ‘lymphoblastic leukemia’, ‘myeloid leukemia’, and ‘therapy’." (PMID 39428967, 2024). "Revumenib (RVB), also known as SNDX-5613, treats KMT2A-rearranged (KMT2Ar) acute leukemias by binding to menin’s binding pocket and displacing KMT2A." (PMID 39768795, 2024). "This offers an epigenetic regulator, such as I1, as an effective epigenetic drug to prevent differentiation block in KMT2A‐r acute leukemia patients, and it would be promising for treating acute leukemias." (PMID 39428967, 2024). "KMT2A‐r acute leukemia typically involves genetic testing to identify the specific KMT2A rearrangement." (PMID 39428967, 2024). "The rearrangement of KMT2A (MLL1) occurs in up to 10% of acute leukemias and is especially common in infant leukemia, with an occurrence rate of at up to 80%." (PMID 36831175, 2023). "Chromosomal translocations that involve the KMT2A gene, which is also known as the mixed-lineage leukemia 1 (MLL1) gene, are the source of a portion of cases of acute leukemia." (PMID 38938622, 2023). "We discovered and validated novel f-circRNAs in acute leukemia harboring KMT2A::AFF1 rearrangements, leading the way to future functional studies aimed to unveil their role in this malignancy." (PMID 36585787, 2023). "KMT2A mutations occur in 5–15% of patients with acute leukemia, while NPM1 is more frequent occurring in nearly 30% of patients with acute leukemia." (PMID 37835461, 2023). "Altogether, 10% of children with acute leukemias harbor rearrangements in KMT2A, a proto-oncogene capable of fusing with more than 100 different partner genes or undergoing partial internal tandem duplication to transform into a potent oncogene." (PMID 38174649, 2023). "Acute leukemia-bearing rearrangements of KMT2A have been recognized as a separate entity by the World Health Organization (WHO) since the introduction of the WHO Classification of Neoplastic Diseases of the Hematopoietic and Lymphoid Tissues in 1999." (PMID 36979800, 2023). "Numerous genomic alterations involving KMT2A have been recognized in acute leukemia, including chromosomal translocations, internal tandem duplications, internal deletions, and amplifications." (PMID 36979800, 2023). "In acute leukemia patients, CDK6 over-expression has been frequently associated with KMT2A translocations, as it has been demonstrated that CDK6 is a direct target of KMT2A fusion proteins." (PMID 36770891, 2023). "Chromosomal rearrangements of the human KMT2A/MLL gene are associated with de novo as well as therapy-induced infant, pediatric, and adult acute leukemias." (PMID 37019990, 2023). "Apart from identifying agents known to be effective against KMT2A-rearranged acute leukemia, our drug screen also provides numerous novel candidate drugs." (PMID 35327440, 2022). "Additional insights from the present study relate to the upregulation of SYK and JAK expression in pediatric and adult KMT2A/MLL-R+ acute leukemias." (PMID 36627892, 2022). "Rearrangements of the Mixed Lineage Leukemia (MLL/KMT2A) gene are present in approximately 10% of acute leukemias and characteristically define disease with poor outcome." (PMID 35677155, 2022). "Mixed-lineage leukemia (MLL) or Lysine Methyltransferase 2A (KMT2A) rearrangements occur in 10% of adult acute leukemias and in 35% of pediatric cases." (PMID 34741119, 2022).
acute leukemia (continued). "MLLT10 is one of the most common fusion partners of mixed-lineage leukemia (MLL, also known as KMT2A) in acute leukemia." (PMID 35126515, 2022). "This, and the fact that various agents were identified that already have been shown to be effective against KMT2A-rearranged acute leukemia, such as BCL-2 inhibitors, HDAC inhibitors, and SN-38, clearly demonstrated the validity of our drug screens." (PMID 35327440, 2022). "Acute leukemias carrying KMT2A (MLL) translocations represent ∼5%–10% of acute leukemia in all age groups and up to 70% of infantile leukemia." (PMID 35301220, 2022). "Chromosomal rearrangements of the mixed-lineage leukemia (MLL, also known as KMT2A) gene were originally discovered in mixed phenotype acute leukemia (MPAL, formerly known as mixed-lineage leukemias)." (PMID 36307883, 2022). "KMT2A-FM is a large FG-FM that has been systematically studied and reported in acute leukemia, with more than 100 partner genes, and their specific breakpoint regions have been identified." (PMID 34135310, 2021). "Six most frequent partner genes (AFF1, MLLT3, MLLT10, MLLT1, ELL, AFDN) are found in about 80% of KMT2A-positive acute leukemias, others are rarer, and for most partner genes only single cases are described." (PMID 34440129, 2021). "Here, we aimed to characterize uncommon KMT2A rearrangements in childhood acute leukemia by conventional karyotyping, FISH, and targeted NGS on both DNA and RNA level with subsequent validation." (PMID 34440129, 2021). "In acute leukemia, 11q23 chromosomal rearrangements, affecting the MLL (KMT2A) gene, are a genetic hallmark and one of the major driver mutations." (PMID 34594227, 2021). "KMT2A rearrangements are an important predictor of outcome in acute leukemia, with the prognosis varying from good and intermediate to poor depending on the partner gene and breakpoint location." (PMID 34440129, 2021). "KMT2A (histone-lysine N-methyltransferase 2A, former MLL)-rearranged acute leukemia represents one type of such neoplasms that are complex both for diagnostics and treatment." (PMID 34440129, 2021). "In human acute leukemia, inter-chromosomal translocations involve in the KMT2A gene, leading to the formation of new chimeric MLL1 fusion proteins, which lose the H3K4 methyltransferase domain." (PMID 32961708, 2020). "MLL1 (KMT2A), which is the mammalian homologue of Drosophila trithorax, is recurrently affected by chromosomal translocations during the development of acute leukemia, leading to the generation of oncogenic fusion proteins." (PMID 33371192, 2020). "Gain-of-function of the mammalian trithorax-homologue MLL1 (KMT2A) is a recurring pattern in cancer, particularly in acute leukemia." (PMID 33371192, 2020). "Pinometostat (Epizyme (EPZ)-5676), a DOT1L inhibitor, was one of the first histone methyltransferase inhibitors to undergo Phase I trials for both children and adults with r/r KMT2A-rearranged acute leukemia." (PMID 32050659, 2020). "Of all the known HMTs, KMT2A or the MLL methyltransferase has the most well-documented role in the development of acute leukemia." (PMID 31192132, 2019). "Rearrangement of the mixed lineage leukemia (MLL, KMT2A) gene occurs in 5–10% of acute leukemias and is especially prevalent in infant acute leukemias (up to 70% of cases)." (PMID 30670779, 2019). "Pinometostat, considered for combination therapies of acute leukemias with KMT2A gene rearrangements, was proved to target DOT1L and reduce H3K79 methylation in adult AML patients with 11q23 translocations." (PMID 31467542, 2019). "The largest family of “multi-partner translocations” in acute leukemia comprises fusions involving the product of the KMT2A (MLL) gene." (PMID 29777171, 2018). "The mixed-lineage leukemia 1 (MLL1) gene (now renamed Lysine [K]-specific MethylTransferase 2A or KMT2A) on chromosome 11q23 is disrupted in a unique group of acute leukemias." (PMID 28232907, 2017).
acute leukemia (continued). "Indeed, one Menin inhibitor, Revumenib, was recently approved for the treatment of patients with relapsed or refractory KMT2A‐rearranged acute leukemia." (PMID 39887730, 2026). "KMT2A‐fusion oncogenes in acute leukemias either recruit DOT1L directly through their fusion partners, such as AF9, AF10, AF17, or ENL, or indirectly to their target genes, thereby fostering an active chromatin environment that counteracts transcriptional repression." (PMID 40181550, 2026). "Similarly, the menin inhibitor revumenib, targeting KMT2A rearrangements and NPM1 mutations in acute leukemia, demonstrated deep and durable remissions in phase I/II studies, culminating in FDA approval in 2024 as the first agent in its class." (PMID 41335282, 2025). "Similarly, Menin inhibitors demonstrate substantial therapeutic effectiveness in treating KMT2A-rearranged and NPM1-mutated pediatric acute leukemias." (PMID 40034590, 2025). "Consequently, there has been great interest in preventing menin from binding to KMT2A protein complexes using small molecules, as several studies showed promising therapeutic potential for KMT2A-rearranged acute leukemia." (PMID 38892207, 2024). "Pinometostat (EPZ-5676), a DOT1L inhibitor, was tested in children with relapsed or refractory acute leukemias harboring MLL (KMT2A) gene rearrangement (MLL-r) as monotherapy in phase I clinical trial (NCT02141828), but no objective responses were observed in this cohort." (PMID 38997742, 2024). "Overall, KMT2A rearrangements are present in up to 10% of acute leukemias." (PMID 39201709, 2024). "Furthermore, KMT2A fusions remain a major adverse prognostic factor in mixed-phenotype acute leukemia (MPAL)." (PMID 38643442, 2024). "This may indicate that recently described biological functions of DOT1L that are independent of H3K79 methylation are also important for KMT2A-rearranged acute leukemia cells." (PMID 37740239, 2023). "If so, the identification of such DOT1L-independent oncogenic properties may well uncover important therapeutic targets and more effective treatment options for KMT2A-rearranged acute leukemias." (PMID 37740239, 2023). "Therefore, targeting DOT1L represents an attractive therapeutic option for patients diagnosed with KMT2A-rearranged acute leukemia, despite the first-in-class DOT1L inhibitor pinometostat showing dissatisfying results in adult patients." (PMID 37740239, 2023). "The interaction between SET and KMT2A, a gene that is frequently rearranged in acute leukemias, might suggest a role for SET in KMT2A-mediated transcription and possibly chromatin maintenance." (PMID 36345878, 2022). "Additionally, the KMT2A-CBL fusion previously reported in acute leukemia was first identified in brainstem gliomas." (PMID 35991838, 2022). "The MLL (MLL1 renamed as lysine-specific methyltransferase 2A or KMT2A) gene on chromosome 11q23 is frequently disrupted by chromosomal rearrangements that occur in the unique group of acute leukemias." (PMID 34298959, 2021). "HOXA upregulation has recently been associated with sensitivity to inhibitors of the KMT2A-Menin complex in KMT2A-rearranged acute leukemia; it would be interesting to assess whether HOXA-upregulating NUMT1-rearranged ALL cells are similarly sensitive." (PMID 34211097, 2021). "Extensive genetic and biological investigations recently revealed opportunities for precision medicine-based treatments that target the distinct vulnerabilities of acute leukemias with KMT2A rearrangements or other genetic alterations that menin inhibitors could target." (PMID 39179671, 2024). "Chromosomal rearrangements involving the lysine (K)-specific methyltransferase 2 A (KMT2A, located on chromosome 11q.23.3, and previously known as mixed lineage leukemias or MLL) are associated with both de novo and therapy-induced infant and pediatric acute leukemias." (PMID 39179671, 2024).
acute leukemia (continued). "Chromosomal rearrangements involving the Mixed Lineage Leukemia gene (MLL1, KMT2A) are defining a genetically distinct subset in about 10% of human acute leukemias." (PMID 39887730, 2026). "Menin inhibitors have entered clinical trials for histone lysine methyltransferase 2 A (KMT2A)-rearranged and nucleophosmin 1 (NPM1)-mutant acute leukemias and are demonstrating promising activity." (PMID 42103719, 2026). "Menin (MEN1) is a well-recognized powerful tumor promoter in acute leukemias (ALs) with lysine methyltransferase 2A (KMT2A, previously known as MLL: mixed-lineage leukemia) rearrangements (KMT2Ar) and mutant nucleophosmin 1 (NPM1m)." (PMID 39796769, 2025). "Recently revumenib, a first in class oral menin inhibitor was approved for patients >1 year of age with relapsed or refractory (R/R) KMT2A-r acute leukemias (AML, ALL or mixed phenotypic acute leukemia [MPAL])." (PMID 41310838, 2025). "KMT2A activates cell proliferation via HOXA9, and MEIS1 upregulation and is therefore a major player in leukemogenesis: roughly every second acute leukemia is characterized by aberrantly increased HOXA9 expression." (PMID 39754404, 2025). "KMT2A rearrangements are not only restricted to the myeloid leukemia, but also occur in acute lymphoblastic leukemia (ALL) and in mixed-phenotype acute leukemia (MPAL)." (PMID 38651453, 2024). "Histone‐lysine‐N‐methyltransferase‐rearranged (KMT2A‐r) acute leukemia, commonly known as mixed lineage leukemia (MLL), is a distinct subtype of acute leukemia marked by genetic abnormalities in the KMT2A gene (also known as ALL‐1, HRX, or HTRX)." (PMID 39428967, 2024). "Lysine [K] methyltransferase 2A (KMT2A, previously known as MLL) gene rearrangements are common in various subtypes of acute leukemia and are related to chemotherapy refractoriness and adverse prognosis." (PMID 38643442, 2024). "Although uncommon, KMT2A::CBL fusion has been reported in both pediatric and adult acute leukemias, including AML and ALL." (PMID 38643442, 2024). "In KMT2A‐r acute leukemia, chromosomal rearrangements disrupt the KMT2A gene, leading to fusion with partner genes, including AF9, ENL, AF4, AFF6, AF10, ELL, and KMT2A‐PTDS, which together are responsible for most KMT2A fusions." (PMID 39428967, 2024). "MLL1 (also known as lysine methyltransferase 2A [KMT2A]) is located on chromosome 11q23, but chromosomal translocation (MLL1-rearrangement [MLL1-r]) occurs in 5%–10% of acute leukemia cases (AML and ALL) in adults and children." (PMID 36841758, 2023). "KMT2A (also known as MLL) is also recurrently rearranged in acute lymphoblastic leukemia (ALL) and mixed phenotype acute leukemia (MPAL) and especially infant ALL is characterized by a high incidence of KMT2A translocations in up to 75% of patients." (PMID 38174649, 2023). "Menin inhibitors disrupt the menin-KMT2A complex in preclinical models of KMT2A-r, NUP98-r and NPM1c acute leukemias and its occupancy at target genes leading to leukemic cell differentiation and apoptosis." (PMID 38174649, 2023). "Rearrangements of the KMT2A gene (alias MLL), located on chromosome 11q23, affect acute leukemias biologically unique for gene expression profiling." (PMID 36672325, 2023). "The lysine(K)-specific methyltransferase 2A gene (KMT2A), previously known as mixed lineage leukemia (MLL), frequently rearranged in acute leukemia, belongs to one of the most promiscuous genes and has been found fused to more than 80 different partners." (PMID 38152368, 2023). "The breakpoints of the KMT2A and CBL genes in Case #3 were different from those in acute leukemia, which should be validated by other methods like RNA-seq." (PMID 35991838, 2022). "Recently, oncogenic rearrangements involving Lysine methyltransferase 2A (KMT2A), a frequent fusion partner in some acute leukemias, have been reported in solid tumors, including types B2 and B3 thymomas and soft tissue sarcomas." (PMID 32461620, 2020).
acute leukemia (continued). "KMT2A (MLL) gene is located in region q23 in chromosome 11 and it is an important member of TrxG family, involved in pediatric acute leukemia pathogenesis." (PMID 31886200, 2019). "DOT1L has been found to be a drug target for acute leukemia with a mixed lineage leukemia (MLL, also known as MLL1 or KMT2A) gene translocation." (PMID 27316347, 2016). "DOT1L is the only known methyltransferase that catalyzes mono-, di- and tri-methylation of lysine 79 on histone H3 (H3K79me1/2/3) and has been identified as a critical component of oncogenic “Mixed Lineage Leukemia 1” (MLL1/KMT2A) complexes in KMT2A-rearranged and NPM1c mutant acute leukemia." (PMID 40781484, 2025). "Unlike the well-established involvement of KMT2A translocations in acute leukemias, the implication of KMT2B, a close paralogue of KMT2A, was reported until recently." (PMID 36594087, 2023). "Targeted next-generation sequencing approaches (NGS) have proven to be affective in the detection of chromosomal aberrations like translocation of ALK and lysine methyltransferase 2A (KMT2A) in lung carcinoma, anaplastic large cell carcinoma and acute leukemias." (PMID 33946969, 2021). "It has been reported that either KMT2A-PTD or Flt3-ITD do not develop AML; however, the cooperation of Flt3-ITD with Kmt2a-PTD developed acute leukemia in a mouse model." (PMID 32015320, 2020). "In our animal model, we could not find an acute leukemia transformation in Kmt2a-PTD mice with DNMT3A-MT, but we observed hematologic abnormalities with shorter latency and hepatosplenomegaly compared to control or DNMT3A-WT mice." (PMID 32015320, 2020).